PDPN (podoplanin)
Diseases named in the same sentence as PDPN in open-access papers (continued):
Sharing a sentence is not in itself a finding about the gene and the disease.
tumor (continued). "In SCCs, cells expressing podoplanin are frequently located at the outer edges of tumor nests, suggesting that cytokines or growth factors secreted by neighboring stromal cells might induce podoplanin expression in the neoplastic epithelium." (PMID 30736372, 2019). "Overall, these results suggest that podoplanin expression in CAFs facilitates their migration into the stroma, where they may affect tumor vascularization." (PMID 30736372, 2019). "The binding of tumor cell PDPN to platelet CLEC-2 triggers platelet activation and aggregation." (PMID 31208371, 2019). "Therefore, SZ168 is an anti-hPDPN mAb that inhibits platelet aggregation induced by tumor cells that express PDPN." (PMID 31208371, 2019). "In tumors, PDPN may play an important role as a regulator of tumor cell migration and invasion, thus contributing to cancer progression and conferring poor prognosis." (PMID 30654768, 2019). "4T1.2 tumor tissue analysis showed laminin-5 furnished around podoplanin+ lymphovasculature." (PMID 31091437, 2019). "With the discovery of molecules targeted at the lymphatic system such as lymphatic vessel endothelial hyaluronan receptor 1 (LYVE-1) and Podoplanin, many studies have been performed to determine the role of lymphatic endothelial cells (LECs) in tumor metastasis." (PMID 31289961, 2019). "On the other hand, podoplanin was detected in EpCAM-containing microparticles isolated from malignant pleural effusions, as well as in microvesicles and exosomes secreted by tumor cell lines." (PMID 30736372, 2019). "Podoplanin-positive LV were detected in 194 (27%) of 709 tumor samples with the mean and median total number of LV determined as 1 and ranging from 1 to 16 LV per tumor fragment." (PMID 31547460, 2019). "In addition, the expression of PDPN by tumor cells can induce tumor lymphangiogenesis and increase lymph nodes metastasis." (PMID 31217907, 2019). "Moreover, several studies have revealed that PDPN is involved in the motility and metastasis of tumor cells." (PMID 31321241, 2019). "Furthermore, we found that SZ168 inhibited tumor growth and suppresses pulmonary metastasis in PDPN-expressing tumors in vivo." (PMID 31208371, 2019). "A recent study also reveals that FAP+PDPN+ CAFs could regulate tumor-specific cytotoxic cell motility and localization through nitric oxide synthase (iNOS)." (PMID 31462327, 2019). "In this context, a recent report found that podoplanin-expressing lymph-node stromal cells promote melanoma growth in vivo by inhibiting anti-tumor specific CD4+ T-cell proliferation and inducing the death of tumor infiltrating CD4+ lymphocytes in a cell-contact-independent fashion." (PMID 30736372, 2019). "This study is aimed to investigate whether blocking PDPN by SZ168 inhibits tumor growth and metastasis." (PMID 31208371, 2019). "These cells use podoplanin to increase motility and survival of neighbouring tumor cells." (PMID 31508790, 2019). "Exploiting this knowledge, PDPN+ myeloid cells could be targeted in combinatorial immunotherapies to enhance immune-mediated tumor destruction." (PMID 30972297, 2019). "In particular, CCL21, which binds podoplanin with high affinity and is secreted by LECs and tumor cells, could facilitate the access of tumor cells to lymphatic vessels." (PMID 30736372, 2019). "Moreover, microthrombi containing podoplanin-positive tumour cells have been reported to become trapped in pulmonary vessels, enabling tumour metastasis." (PMID 30745334, 2019). "Functional experiments performed in cell lines suggest that PDPN regulates the tumor cell motility." (PMID 30654768, 2019). "More recently, we generated PG4D2, a neutralizing antibody recognizing the PLAG4 domain in human podoplanin and found that it strongly suppressed podoplanin–CLEC-2 binding and podoplanin-mediated hematogenous metastasis of human podoplanin-expressing tumor cells inoculated into mice." (PMID 30279963, 2018).
tumor (continued). "Thus, COX-2, podoplanin and galectin 3 are obviously intertwined in their support to tumor growth in different fashions and highlight COX-2 as valuable target in lymphangiogenesis." (PMID 30305116, 2018). "In our previous results obtained by using several anti-podoplanin neutralizing antibodies, pulmonary metastasis of cancer cells was suppressed by the intravenous injection of anti-podoplanin neutralizing antibody on 1 hour to 3 days before tumor injection." (PMID 30279963, 2018). "Interestingly, despite the unchanged primary tumor growth, PDPN-tk-GCV mice with tumors exhibited significantly fewer surface metastatic lung nodules and histologically identified lung metastases when compared to WT mice." (PMID 30592710, 2018). "PDPN expresses in various tumours during migration and metastasis." (PMID 30544833, 2018). "IDO-positive tumor-associated vessels were studied by 7-color multiplex immunohistochemistry using the markers CD31/CD34 (endothelial cell markers), podoplanin (lymphatic endothelial cell marker), α-sma (perivascular cell marker), galectin-1 (activated endothelial cell marker), and IDO." (PMID 30050535, 2018). "mECK36 tumor formation show consistent expression of the KS markers Podoplanin and LYVE-1, occurring with concomitant up-regulation of KSHV lytic oncogenes and angiogenesis ligands/ receptors, pointing to the upregulation of various receptor tyrosine kinase signaling axes." (PMID 29985958, 2018). "To better define the mechanisms underlying the tumor-supportive function of Il7-expressing CAFs, we compared the gene expression profiles of sorted EYFP+PDPN+ (designated ‘EYFP’) and EYFP−PDPN+ (designated ‘PDPN’) CAFs from E0771 tumors growing in Il7-EYFP mice." (PMID 29632733, 2018). "In these cases, PDPN may enhance the tumor-promoting effects of CAFs due to increased RhoA activity." (PMID 29765527, 2018). "PDPN could be related to tumor growth, leading to poor prognosis, and its expression might be determined by the genotype of each tumor." (PMID 28702871, 2018). "When mice were injected intravenously with CAFs and tumor cells simultaneously, it was found that PDPN-high CAFs invaded in larger amounts and promoted cancer cell invasion into the lung parenchyma, more than with PDPN-low CAFs." (PMID 28938000, 2017). "Podoplanin expressed on CAFs affects the biological properties of tumor cells." (PMID 28938000, 2017). "Our data suggest that the inhibition of PDPN-ROCK signaling can suppress tumor formation itself." (PMID 28059107, 2017). "However, we cannot exclude the possibility that actually, tumor-born PDPN-positive fibroblasts with high motility migrate efficiently from tumor to surrounding tissues, helping cancer cells during their invasion." (PMID 28938000, 2017). "Moreover, the importance of PDPN in the tumor microenvironment was confirmed by assessing the effect of its expression on micro RNAs (miR-21, miR-210, miR-29b) that are involved in tumor development." (PMID 28416768, 2017). "It has been proposed that podoplanin-expressing CAFs stimulate tumor cell migration and invasiveness, however, the role of this glycoprotein in both processes remains unclear." (PMID 28938000, 2017). "The expression of PDPN protein was completed detected on cellular membrane in tumor cells." (PMID 28086225, 2017). "Both of the positive expression rates of LYVE–1 in tumor tissues and para-cancerous tissues were 100%, and the same results could be found for Podoplanin." (PMID 29162097, 2017). "This confirms an antiadhesive effect of PDPN in the tumor stroma." (PMID 28416768, 2017). "Wicki and Christofori showed that invasion of podoplanin- expressing tumor cells was correlated with an overexpression of matrix metalloproteinases (MMPs) and it could be inhibited by specific inhibitors of MMPs." (PMID 29410757, 2017).
tumor (continued). "Further study, using a mutated form of podoplanin lacking an intracellular domain, revealed that the tumor-promoting activity of PDPN is associated with increased activity of RhoA." (PMID 28938000, 2017). "In addition, administration of antiplatelet agent or podoplanin-neutralizing antibody suppressed the growth of LSCC tumour xenografts by inhibiting EGFR phosphorylation in vivo." (PMID 28642617, 2017). "Therefore, significant positive correlation (r = 0.694, p < 0.0001) between the expression of podoplanin in peripheral stroma at the margin of tumor and tumor stroma was found using Spearman’s correlation analysis." (PMID 28938000, 2017). "First, the PDPN-positive fibroblasts were found in peripheral stroma at the margin of tumor and their numbers correlated with numbers of podoplanin expressing CAFs in tumor stroma, what suggests that at least part of PDPN-positive CAFs comes from outside the tumor." (PMID 28938000, 2017). "Moreover, some podoplanin mAbs reportedly show the suppression of in vivo hematogenous metastasis not only using podoplanin-expressed CHO cells but also using podoplanin-positive human tumor cell lines." (PMID 28674748, 2017). "Recent studies on ductal breast cancer revealed that the presence of CAFs expressing podoplanin positively correlated with tumor size, degree of malignancy, lymph node metastases, invasion into lymphatic and blood vessels, expression of Ki67 antigen, shorter patients’ survival and VEGF-C expression." (PMID 28938000, 2017). "At least, MS-1 mAb exhibits anti-tumor activity against podoplanin-positive PC-10 xenograft tumor in immune-deficient NOD-SCID mouse, and the recombinant single-chain antibody variable region fragment of MS-1 also suppresses podoplanin-mediated metasiasis." (PMID 28674748, 2017). "Moreover, we also found the colocalization of platelet aggregates, detected by anti-fibrin/fibrinogen antibody, with strong PDPN staining in PC-10 tumour." (PMID 28642617, 2017). "The role of PDPN in carcinogenesis and tumor progression has been studied intensively." (PMID 28938000, 2017). "Treatment of mice with a TGF-β-neutralizing antibody statistically suppressed podoplanin-mediated distant metastasis in vivo, suggesting that podoplanin promoted haematogenous metastasis in part by releasing TGF-β from platelets that was essential for EMT of tumour cells." (PMID 28176852, 2017). "We thus propose that podoplanin increases the invasive properties of fibroblasts by increasing their migratory properties without affecting the expression of matrix metalloproteinases, which allow them to “colonize” tumor stroma in higher numbers." (PMID 28938000, 2017). "Podoplanin might favour tumor invasion through its ability to remodel actin in the cytoskeleton of tumor cells, resulting in increased motility." (PMID 29410757, 2017). "Moreover, podoplanin expression was found in tumour-initiating cells, suggesting a pathological role for podoplanin in tumour progression." (PMID 28176852, 2017). "Thus, we here investigated the role of podoplanin-mediated platelet aggregation in tumour invasiveness and extravasation." (PMID 28176852, 2017). "Ligation of CLEC-2 with podoplanin elicits strong platelet activation, and it is identified that platelet activation is known to promote tumor metastasis, which may be triggered by podoplanin up-regulation." (PMID 27564117, 2016). "Thus, podocalyxin likely acts in subtly different ways from podoplanin, which is another small mucin that initiates collective tumor cell motility by inducing the formation of filopodial rather than lamella-like structures." (PMID 26796961, 2016). "Podoplanin was identified as a key protein responsible for the tumor-promoting effect of CNT-induced CAFs and thereby could be a novel candidate biomarker for initial screening of the carcinogenicity of CNTs and related nanomaterials." (PMID 27996035, 2016).
tumor (continued). "Thus, precise analysis of the mechanisms of podoplanin-mediated platelet aggregation is critical for developing anti-tumor therapies." (PMID 26684030, 2016). "On the other hand, CLEC-2 ligation with podoplanin could elicit strong platelets activation, which protects them from shear stress and NK cells in the blood stream and serves for tumor cell nestling." (PMID 27564117, 2016). "We previously identified podoplanin as a key factor in tumor-induced platelet aggregation." (PMID 26684030, 2016). "Also, in the present study we have observed a podoplanin expression at the advancing edge, mainly at the periphery of tumor proliferations, suggesting its involvement in tumor invasiveness." (PMID 27871286, 2016). "Downregulation of podoplanin in LFs by RNA interference strongly inhibited CNT-induced CAF-like cells and their effects on CSCs and subsequent tumor formation, providing new insights into the role of podoplanin in CSC growth and maintenance mediated by CAF-like cells." (PMID 27996035, 2016). "PDPN is a transmembrane mucin-like protein that augments tumor cell invasion." (PMID 25826087, 2015). "PDPN is necessary and sufficient to increase tumor cell migration." (PMID 25826087, 2015). "All these suggest that podoplanin may play some role in the regulation of differentiation, growth, and tumor progression of OSCC." (PMID 26558136, 2015). "Inhibitors of CLEC-2 which prevent the binding of of CLEC-2 with podoplanin on T cells may prove useful in reducing immunosuppression in tumor microenvironment." (PMID 26416420, 2015). "In addition to playing a role in TCIPA, PDPN is upregulated in the front end of the invasive margin of a tumor mass and is involved in the collective cell invasion process independent of the non-epithelial-mesenchymal transition of cancer cells." (PMID 26528756, 2015). "Although its biological function is not yet clearly understood, a number of previous reports have suggested that podoplanin may act as a mediator of tumor cell invasion and metastasis." (PMID 26622791, 2015). "Antibodies against PDPN can be used to inhibit tumor progression." (PMID 25826087, 2015). "In tumors, podoplanin is involved in tumor cell-induced platelet aggregation and tumor metastasis." (PMID 26416420, 2015). "PDPN expression is induced by tumor promoters including TPA, RAS, and Src." (PMID 25826087, 2015). "Podoplanin (PDPN) is a unique transmembrane receptor that promotes tumor cell motility." (PMID 25826087, 2015). "Thus, we cannot rule out the possibility, that when the analysis will be performed on a larger group of PTCs the association between tumor size and podoplanin expression, or tall cell variant of PTC and PDPN positivity, will be found." (PMID 24797369, 2014). "Our findings and other available data indicate that the uncharacterized mechanisms by which PDPN affects the aggressive phenotype of cancer cells are complex and may be dependent on the examined tumor tissue." (PMID 24797369, 2014). "Interestingly, in DU145-LN4 tumors K18-positive tumor emboli were also clearly visible inside lymphatic vessels in the peritumoral stroma, as visualized by double staining with podoplanin (black color) and K18 (brown color)." (PMID 24885350, 2014). "Podoplanin (PDPN), a mucin-type transmembrane glycoprotein specific to the lymphatic system is expressed in a variety of human cancers, and is regarded as a factor promoting tumor progression." (PMID 24797369, 2014). "Although some data indicate that the expression of podoplanin in tumor cells might be related to their malignant potential, the functional contribution of this protein to cancer progression, invasion and metastasis remains unclear." (PMID 24797369, 2014). "As podoplanin is correlated with other proteins involved in cell proliferation and tumor invasion, its downregulation may be due to limited activity of the odontogenic epithelium after the surgical approach." (PMID 25480364, 2014).
tumor (continued). "Immunofluorescence analysis revealed that mECKnull.rK133 tumor cells expressed markers implicated in KS pathogenesis such as the vascular marker VEGF-R2 and podoplanin, a lymphatic endothelial KS marker, but they did not express the EPC marker, CD133 (data not shown)." (PMID 24489895, 2014). "Furthermore, a genetic dissection of PDPN function in malignant cells versus in the surrounding tumor stroma will significantly advance our understanding of this molecule in cancer." (PMID 22988448, 2012). "It is possible that expression of PDPN in leukocytes leads to similar downstream changes as in tumor cells; however, it is likely that PDPN interacts with different molecules and signaling pathways in stromal cells and leukocytes than in malignant cancer cells." (PMID 22988448, 2012). "PDPN is a unique transmembrane receptor that promotes tumor cell motility." (PMID 22844530, 2012). "PDPN is activated by endogenous ligands to induce tumor cell motility and metastasis." (PMID 22844530, 2012). "Podoplanin expressions significantly decreased as the tumor classification levels increased." (PMID 24551781, 2012). "Our data demonstrate that MASL targets PDPN to inhibit tumor cell growth and motility." (PMID 22844530, 2012). "There is a wealth of data on the tumor-promoting effects of CAFs, which has been reviewed elsewhere, but only recently have specific functions for PDPN on CAFs been examined." (PMID 22988448, 2012). "Furthermore, recent studies of PDPN expression by leukocytes have demonstrated that PDPN expression has intrinsic effects on these cells as well as tumor cells." (PMID 22988448, 2012). "PDPN expression can be induced by tumor promoters including TPA, oncogenic Ras, and Src." (PMID 22844530, 2012). "On the other hand, podoplanin is crucial for processes involving cell migration, such as the specific embryologic development of deep lymphatics and the invasion and metastasis of certain tumour cells or tissues." (PMID 21385358, 2011). "The correlations of NF-κB and Notch1 with lymph node involvement, lymphatic vessel density (LVD), podoplanin, and vascular endothelial growth factor-C (VEGF-C) were further evaluated to determine the association of NF-κB and Notch1 expression with tumor-induced lymphangiogenesis." (PMID 21939555, 2011). "In one case (autopsy, No. 70) which showed only a few nuclei with positive IR for Calretinin and positive membranous IR for EMA in less than 25% of cells, the combination Podoplanin and Mesothelin, with IR in two and three quartiles of tumour cells, respectively, would have been a better option." (PMID 20602796, 2010). "Podoplanin expression was also detected in tumour cells at the tumour border." (PMID 20698954, 2010). "In addition, podoplanin expression in these tumours inversely correlated with lymphatic invasion and lymph node metastasis." (PMID 20196862, 2010). "In addition, podoplanin expression was also significantly higher in well-differentiated tumours, which are usually less invasive than those poorly differentiated." (PMID 20196862, 2010). "Podoplanin, a mucin-like transmembrane glycoprotein, is reportedly expressed in a variety of malignant cells and is generally regarded as a factor for promoting tumor progression in conventional studies." (PMID 21034514, 2010). "First, we confirmed exogenous podoplanin expression in tumor tissue." (PMID 21034514, 2010). "The expression of podoplanin in human cancers and its relationship with tumour invasion raises the possibility that podoplanin expression could be used as a biomarker for diagnosis and prognosis." (PMID 20196862, 2010). "Hitherto-existing evidence relating to podoplanin functions can not explain the mechanism underlying the tumor suppression." (PMID 21034514, 2010). "This could be explained by the fact that podoplanin expression was higher in early-stage tumours and, interestingly, all cases that developed distant metastasis showed low podoplanin expression." (PMID 20196862, 2010).